COX18 (cytochrome c oxidase assembly factor COX18)
Description:
Mitochondrial membrane insertase required for the translocation of the C-terminus of cytochrome c oxidase subunit II (MT-CO2/COX2) across the mitochondrial inner membrane. Plays a role in MT-CO2/COX2 maturation following the COX20-mediated stabilization of newly synthesized MT-CO2/COX2 protein and before the action of the metallochaperones SCO1/2. Essential for the assembly and stability of the mitochondrial respiratory chain complex IV (also known as cytochrome c oxidase).
Synonyms: COX18Hs; OXA1L2; FLJ38991; CMT2MM; MC4DN25
Tractability: Antibody: UniProt predicts a signal peptide or a membrane-spanning region. PROTAC: ubiquitination databases record sites on it; its protein half-life has been measured.
Gene: Protein-coding gene on chromosome 4 (73,052,362 to 73,069,755, reverse strand). Ensembl gene ENSG00000163626.
Subcellular location: Mitochondrion inner membrane
Pathways (Reactome):
Metabolism: Complex IV assembly
Gene Ontology:
Molecular function: membrane insertase activity; protein binding
Biological process: mitochondrial respiratory chain complex IV assembly; protein insertion into mitochondrial inner membrane from matrix; protein insertion into mitochondrial membrane; respiratory chain complex IV assembly; protein insertion into membrane
Cellular component: mitochondrial inner membrane; mitochondrion; membrane
Genetic constraint (gnomAD): Loss-of-function variants: 34 observed, 26.81 expected, observed/expected ratio (o/e) 1.27, 90% interval 0.96 to 1.68. The upper end of that interval is the gene's LOEUF score, 1.68, which puts it in group 6 of 6, group 1 being the genes least tolerant of losing a copy. Missense variants: 414 observed, 356.27 expected, observed/expected ratio (o/e) 1.16, 90% interval 1.07 to 1.26. Synonymous variants: 163 observed, 145.01 expected, observed/expected ratio (o/e) 1.12, 90% interval 0.99 to 1.28.
Homologues: Orthologues: chimpanzee COX18 (100% identical), macaque COX18 (94% identical), pig COX18 (85% identical), rabbit COX18 (81% identical), dog COX18 (78% identical), mouse Cox18 (78% identical), rat Cox18 (75% identical), guinea pig COX18 (67% identical), tropical clawed frog cox18 (56% identical), zebrafish cox18 (51% identical), Drosophila melanogaster CG4942 (34% identical). Paralogues in human: OXA1L (23% identical).
Diseases named in the same sentence as COX18 in open-access papers:
COX18 is named in the same sentence as 14 diseases in open-access papers, as found by Europe PMC text mining. Sharing a sentence is not in itself a finding about the gene and the disease. The quoted sentences say what the papers report.
mastitis (2 papers, 2023 to 2025). Inflammation of breast tissue during lactation or postpartum due to an obstructed duct or infection. "The COX18 gene was much less expressed in cows with mastitis as compared to healthy Holstein and Montbéliarde dairy cows." (PMID 40005882, 2025). "The greatest potential levels of mRNA were found for the mastitis-affected dairy cows’ NFkB (2.63 ± 0.11) and COX18 (2.64 ± 0.16) genes, respectively, while CHL1 (0.44 ± 0.12 and 0.64 ± 0.11) had the lowest levels in both Holstein and Montbéliarde dairy cows." (PMID 36669036, 2023).
neuropathy (2 papers, 2025 to 2026). A disorder affecting the nervous system that manifests with pain, tingling, numbness, and/or muscle weakness. "Notably, bi‐allelic COX18 pathogenic variants have been molecularly linked to severe mitochondrial disorders characterised by progressive encephalomyopathy and neuropathy, as demonstrated in recent clinical case reports with biochemical validation of respiratory chain deficiencies." (PMID 40551575, 2025). "COX18-related neuropathy showed notable inter- and intrafamilial phenotypic variability." (PMID 40830826, 2026).
Arthritis (1 paper, 2025). Inflammation of a joint. "When comparing healthy rams to those with arthritis, the expression levels of the following genes were noticeably higher: IL-1α, IL-1β, IL-6, IL-10, TNFα, NCF4, NFKB, TMED, FCAMR, iNOS and COX18." (PMID 40005882, 2025). "The rams with arthritis showed significantly greater levels of gene expression for the genes IL-1α, IL-1β, IL-6, IL-10, TNFα, NCF4, NFKB, TMED, FCAMR, iNOS and COX18 than did the healthy rams." (PMID 40005882, 2025). "Gene expression intensities were much higher in the arthritis-affected rams than in the healthy ones for the genes IL-1α, IL-1β, IL-6, IL-10, TNFα, NCF4, NFKB, TMED, FCAMR, iNOS and COX18." (PMID 40005882, 2025). "This research described the antioxidant (SOD3, CAT, GPX, ATOX1 and COX18) and immunological (IL-1α, IL-1β, IL-6, IL-10, TNFα, NCF4, NFKB, TMED, FCAMR and iNOS) genes in rams that had arthritis and those that did not." (PMID 40005882, 2025).
leukemia (1 paper, 2022). A malignant (clonal) hematologic disorder, involving hematopoietic stem cells and characterized by the presence of primitive or atypical myeloid or lymphoid cells in the bone marrow and the blood. "To validate the function of SETD1A target genes (COX15, HMBS, UROS, RRNAD1, NUDT18, GSTZ1, HINT2, and COX18) in leukemia cells, we performed a CRISPR-based competitive cell proliferation assay in doxycycline-inducible Cas9-expressing MOLM-13 leukemia cells." (PMID 36450243, 2022). "In contrast, COX18, the other SETD1A-dependent complex IV assembly factor, was dispensable for leukemia cell growth as well as OCR." (PMID 36450243, 2022).
lymphoma (1 paper, 2020). A malignant (clonal) proliferation of B- lymphocytes or T- lymphocytes which involves the lymph nodes, bone marrow and/or extranodal sites. "In our study, mutations in COX18 occurred frequently, but only in lymphomas in the ‘good’ responder group." (PMID 32857815, 2020).
cancer (2 papers, 2020 to 2022). A tumor composed of atypical neoplastic, often pleomorphic cells that invade other tissues. "Two genes had variants found in the cancers of at least two 'good’ responders but in no 'poor’ responders: COX18 and ENSCAFG00000030512." (PMID 32857815, 2020).
tumor (1 paper, 2020). "Since COX18 codes for a widely used metabolic enzyme, absence thereof might severely impact tumor cell growth and survival." (PMID 32857815, 2020).
COX18 also shares sentences with these, for which no sentence is quoted: Charcot-Marie-Tooth disease type 2 (1 paper); encephalomyopathy (1); hearing loss (1); lung carcinoma (1); mitochondrial disease (1); peripheral neuropathy (1); Sensorimotor neuropathy (1).